EIF4E (eukaryotic translation initiation factor 4E)
Diseases named in the same sentence as EIF4E in open-access papers (continued):
Sharing a sentence is not in itself a finding about the gene and the disease.
autism (continued). "Several of these genes have strong or suggestive associations with autism, according to their SFARI scores (e.g., EIF4E–Score 2; CDKL5-Score 1S)." (PMID 41367385, 2025). "Research has indicated a correlation between the overexpression of eIF4E gene and autism-like social cognitive impairment." (PMID 39557567, 2024). "In the current work, authors first repeated the autism-like social cognitive deficits in eIF4E overexpression mice with different behavior tests." (PMID 39557567, 2024). "In the context of APPIN5, EIF4E serves as a hub protein within the autism network, while also being closely interconnected with the mTOR signaling pathway and the circadian clock." (PMID 37807632, 2023). "Deletion of the eIF4F complex related proteins, such as eIF4E or 4EBP2, produce autism-related behavioral phenotypes and social behavioral deficits in animal models." (PMID 33802132, 2021). "Pharmacological treatments based on inhibition of this pathway have been developed and tested in mouse models for Fragile X syndrome, eIF4E dysregulation, and TSC1 and TSC2, with amelioration of autism-associated deficits in all cases." (PMID 31548888, 2019). "Translation has been an important topic in ASD primarily because of work on syndromic forms of autism related to mutations in FMR1, TSC1/2, and PTEN, as well as the important cap-dependent translation gene EIF4E." (PMID 28649314, 2017). "Genomic sequence analyses of the eIF4E promoter region identified a SNP in autism patients that enhanced the promoter activity of eIF4E." (PMID 24605088, 2014). "Mutations in the genes encoding various factors that regulate translation (eIF4E, eIF4G1, GRB10‐interacting GYF protein 1 (GIGYF1), GIGYF2, and zinc finger protein 598) were identified in people with autism (Simons Foundation Autism Research Initiative, SFARI database)." (PMID 41236931, 2025). "Nevertheless, it remains unclear whether there is an involvement of the hippocampus and OXT in autism-like social cognitive impairments due to eIF4E overexpression." (PMID 39557567, 2024). "In addition, previous animal studies have shown that transgenic mice overexpressing eIF4E exhibit abnormal hippocampal neuronal functions and behaviors resembling autism-like social cognitive impairments." (PMID 39557567, 2024). "Our results suggest that reduced oxytocin levels may be a factor contributing to the development of autism-like behaviors due to overexpression of eIF4E." (PMID 39557567, 2024). "In that study, the authors suggested that the cascade ERK1-2/Mnk1/eIF4E may constitute a molecular signature predictive for the early diagnosis of autism, notably severe ASD." (PMID 35626639, 2022). "Additionally, autism-like phenotypes have been observed in Eif4ebp2 knockout and eIF4E-overexpressing mice, both downstream mTOR effectors regulating protein translation." (PMID 25627160, 2015). "Notably, administration of the mTORC1 (mTOR complex 1) inhibitor rapamycin improved sociability in the BTBR mouse model of ASDs; targeting downstream mTOR signaling such as eukaryotic translation initiation factor 4E (eIF4E) also reversed autism." (PMID 25767435, 2015). "Interestingly, genetically increasing the levels of eukaryotic translation initiation factor 4E (eIF4E) in mice results in exaggerated cap-dependent translation and behaviors reminiscent of autism." (PMID 24273493, 2013). "Hence, our finding adds EIF4E to the growing list of genes that may be related to both CHDs and neurodevelopment disabilities such as autism." (PMID 31314787, 2019). "Dysregulation of the mTOR/eIF4E axis disrupts the clock and engenders ASD-like phenotypes in animals, indicating potential crosstalk between the brain clock and autism." (PMID 34943821, 2021). "Finally, as we identified four proteins (p-eIF4E, rpS6, TSC1 and p-MNK1) that demonstrated an association with the clinical severity, we wanted to investigate if, together, those proteins could constitute a molecular signature for autism severity." (PMID 30705255, 2019).
autism (continued). "Overexpression of eIF4E has been shown to lead to autism-like behavior in mice, and HIV-1 was shown to be able to maintain virus-specific protein synthesis when eIF4E is downregulated." (PMID 24833669, 2014). "Epigenomic analysis of white blood cell DNA in newborns with autism has revealed elevated expression of the eIF4E gene compared with those without autism." (PMID 39557567, 2024). "Conversely, in our study, autistic subjects had significantly decreased p70S6K and eIF4B, while there were no changes in 4E-BP1 or eIF4E in these patients, pointing to specific deficits in mTOR-dependent translation via the p70S6K/S6 pathway in idiopathic autism." (PMID 25627160, 2015).
colorectal cancer (29 papers, 2014 to 2026). A primary or metastatic malignant neoplasm that affects the colon or rectum. "We found that breast and colorectal cancers were significantly associated with the expression of eIF4E (DSS: disease-specific survival; RFS: relapse-free survival)." (PMID 34876062, 2021). "Our results herein demonstrated that eIF4E was a protein associated with colorectal carcinoma metastasis and played a key regulatory role in the lethal metastasis process of the tumor." (PMID 27907907, 2016). "Studies have also shown that high expression of eIF4E in invalids with colorectal cancer predict high risk of hepatic metastases and their related mechanism may be partly by the regulation of the levels of VEGF, cyclin D1, MMP-2, and MMP-9." (PMID 36118897, 2022). "However, in the present study, p-eIF4E may associate with the negative regulation of eIF4E activity, as indicated in some other tumours including ovarian, gastric, and colorectal cancers." (PMID 31258849, 2019). "In colorectal cancer, downstream molecules of the mTOR pathway such as eukaryotic translation initiation factor 4E (eIF4E) and eukaryotic translation initiation factor 4E-binding protein 1 (4E-BP1), play a crucial role in cancer development." (PMID 39349424, 2024). "Compound 4 treatment disrupted eIF4G binding to eIF4E determined by co-immunoprecipitation with an eIF4E antibody from SW620 human colorectal cancer cell lysates." (PMID 40016190, 2024). "For these features, EIF4E has been identified as a target of a second-generation antisense oligonucleotide called ISIS 183750 for the treatment of colorectal cancer." (PMID 36012138, 2022). "The significance of the EIF family member eIF-4E with perineural invasion was reported in colorectal cancer, and the correlation between EIF3B and PNI in HNSCC was first reported in this study." (PMID 35459206, 2022). "In the case of colorectal cancer, the combination of αvβ6 with eIF4E (eukaryotic translation initiation factor 4E) or Ets-1 was found to determine an effective prognosis." (PMID 36293202, 2022). "The phosphorylation of 4EBP1 and eIF4E was measured 6 h after polyamine addition, based on our previous data in colorectal cancer cells where intracellular polyamines shows uptake saturation after 3–4 h of cells exposure to exogenous polyamines." (PMID 36135836, 2022). "For example, ISIS 183750 targeting eIF4E has been tested in clinical trials in patients with advanced stage colorectal cancer." (PMID 33923168, 2021). "Increased levels of phospho-eIF4E were also observed in gastric and colorectal cancers, whereas overexpression of MNK1 in epithelial ovarian cancer correlates with phospho-eIF4E levels and poor clinical outcome." (PMID 32517051, 2020). "Reduction of eIF4E in colorectal cancer cells suppresses the invasion and migration by modulating the expression of MMPs and VEGF." (PMID 32967226, 2020). "For example, ISIS 183750, which is an ASO drug against eIF4E, disrupts the proliferation of colorectal cancer cells and shows a synergetic effect with the chemical drug, irinotecan." (PMID 32967226, 2020). "Among these miRNAs, miR-497 is down-regulated in breast, gastric, and colorectal cancer and promotes cell proliferation and invasion by up-regulating raf-1/Ccnd1, EIF4E, and insulin growth factor 1 receptor in breast, gastric, and colorectal cancer." (PMID 27531900, 2016). "Through IHC followed by statistical analysis, the percentage of eIF4E positive cases in all patients with colorectal cancer was 91.7% (99/108)." (PMID 27907907, 2016). "In the study, we investigated the expression of eIF4E in 108 colorectal carcinoma and adjacent normal tissues." (PMID 27907907, 2016). "Since the loss of 4E-BP1 or eIF4E overexpression can promote tumorigenesis, the ratio of 4E-BP1 to eIF4E in colorectal cancer cells was also evaluated." (PMID 26204490, 2015).
colorectal cancer (continued). "It was shown that eIF4E level in colorectal cancer cell lines was higher than that in controls." (PMID 36118897, 2022). "eIF4E is highly upregulated in colorectal cancer patients with metastatic tissues in liver." (PMID 32967226, 2020). "MicroRNA-497 has been reported to inhibit thyroid cancer tumor growth and invasion by suppressing BDNF, which is involved in cell proliferation and invasion of gastric cancer by repressing eIF4E, and to inhibit colorectal cancer growth by targeting insulin-like growth factor 1 receptor." (PMID 33015042, 2020). "More interestingly, eIF4E also regulates the expression of MMP-2 in colorectal cancer." (PMID 27907907, 2016). "In colorectal cancer (CRC) tissues, the expression of eIF4E is positively correlated with PRMT5, silencing PRMT5 leads to decreased eIF4E expression." (PMID 37601696, 2023). "In their experiment, PRMT5 knockdown led to decreased eIF4E and FGFR3 gene expression while PRMT5 was overexpressed in colorectal cancer cells, correlating with decreased overall patient survival." (PMID 33440687, 2021). "To better understand a role of eIF4E S209 in oncogenic translation, we generated EIF4ES209A/+ heterozygous knockin (4EKI) HCT 116 human colorectal cancer (CRC) cells." (PMID 33135632, 2020). "The study aimed to investigate the expression, clinical significance and function of eIF4E, VEGF-C, E-cadherin, and MMP2 in colorectal cancer and determine the potential of eIF4E, VEGF-C, E-cadherin and MMP2 as indicators of colorectal cancer." (PMID 27907907, 2016). "We also determined the expression levels of eIF4E and p-4E-BP1 in colorectal cancer cell lines and normal cells." (PMID 26204490, 2015). "EIF4E and p-4E-BP1 were upregulated in most colorectal cancer cells under normoxia and hypoxia." (PMID 26204490, 2015). "However, although originally promising, this approach reduced eIF4E expression, but did not substantially improve clinical responses in patients with advanced solid tumors, including colorectal cancer." (PMID 31903169, 2019).
lung carcinoma (28 papers, 2010 to 2025). "The research on mice with loss of eIF4E gene function shows that 50% reduction of eIF4E is compatible with normal development of the body and has a significant inhibitory effect on KRas driven lung cancer initiation." (PMID 35737644, 2022). "In the transgenic mouse model, the overexpression of EIF4E caused B cell lymphoma, lung cancer, liver cancer and angiosarcoma." (PMID 22734884, 2012). "However, in lung and gastric cancers, decreased expression of eIF4E was significantly associated with poor prognosis (lung cancer OS HR =0.86, 95% CI =0.76–0.98, P = 0.019; gastric cancer OS HR =0.54, 95% CI =0.44–0.65, P = 1.1e-10)." (PMID 34876062, 2021). "The current study found elevated phosphorylation levels of eIF4E and 4EBP1 in gefitinib-resistant lung cancer cells, which declined upon the downregulation of c-kit expression." (PMID 39744423, 2025). "Mechanistically, c-kit was found to regulate the AKT/mTOR/4EBP1/eIF4E axis, promoting stemness and gefitinib resistance in lung cancer cells." (PMID 39744423, 2025). "The molecular investigations indicated that c-kit regulated the AKT/mTOR/4EBP1/eIF4E axis, thus driving the transformation of the stemness phenotype in gefitinib-resistant lung cancer cells." (PMID 39744423, 2025). "In the present study, our results revealed that p‐eIF4E was overexpressed in both LADC and LSCC tissues and associated with poor OS of patients with lung cancer, which was in agreement with previous literature." (PMID 40308810, 2025). "EIF4E regulates gene translation and has been proved to play an important role in the progression of lung cancer." (PMID 37601696, 2023). "The absence of eIF4E eliminates the effect of rifabutin on the inhibition of β-Catenin activity, which further confirms that rifabutin plays a role in lung cancer cells by targeting eIF4E and β-Catenin." (PMID 37601696, 2023). "When MnK inhibitors were applied to in vitro and in vivo models of melanoma, lymphoma, colon cancer, and lung cancer, blocking the phosphorylation of eIF4E was found to inhibit cell proliferation and metastasis." (PMID 32967226, 2020). "The active form of MNK1, p-MNK1 (Thr197/202), and phosphorylated eIF4E, p-eIF4E, are increased in lung cancer and correlate with poor overall survival of NSCLC patients." (PMID 32340135, 2020). "N-7 benzyl guanosine monophosphate tryptamine phosphoramidate prodrug (4Ei-1) prevents eIF4E cap binding and triggers proteasomal degradation of eIF4E, thereby chemosensitizing breast and lung cancer to gemcitabine." (PMID 32967226, 2020). "MNK1/2 inhibitors of phosphorylation of eIF4E plus rapalogs have been shown to have an additive tumor growth inhibition in experimental models of glioblastoma, prostate, and lung cancer." (PMID 31878201, 2019). "FGFR3 and eIF4E were previously reported to frequently overexpress in lung cancer, myeloma, and ovarian cancers, thus playing an important role in tumor occurrence and development." (PMID 29545752, 2018). "Phosphorylation of eIF4E is elevated in a wide variety of human cancers and is a prognostic marker in lung cancer." (PMID 27050281, 2016). "This implied that c-kit could regulate the stemness phenotype transformation in gefitinib-resistant lung cancer cells through the AKT/mTOR/4EBP1/eIF4E axis." (PMID 39744423, 2025). "In addition, as a tryptamine phosphoramidate prodrug of 7-benzyl guanosine monophosphate (7Bn-GMP), 4Ei-1 blocks eIF4E cap binding and triggers proteasomal degradation of eIF4E, thereby overcoming gemcitabine resistance in breast and lung cancers." (PMID 40271197, 2025). "Consequently, to detect the influence of inhibiting eIF4E phosphorylation on lung cancer cells in vitro, we used the mouse lung cancer cell LL2 and the human NSCLC cell line H460 for in vitro experiments by Cell Counting Kit‐8 (CCK‐8) assay." (PMID 40308810, 2025).
lung carcinoma (continued). "On the other hand, concerning the relationship between mTOR and the expression of eukaryotic initiation factor-4E (eIF-4E) in lung cancer, there is evidence suggesting an involvement of the mTOR pathway in lung carcinogenesis via its binding to eIF-4E, acting as an oncogene in numerous studies." (PMID 36428613, 2022). "Moreover, in some types of cancer, including lung cancer, phosphorylated eIF4E levels were found significantly elevated only in early-stage but not in late stage tumors." (PMID 33092114, 2020). "Further, the MYC expression is positively associated with AXL, EIF4E, and EMT signatures and both mRNA and protein levels of the EIF4E are of prognostic significance in KRAS-mutant lung cancer, lung adenocarcinoma, and lung cancer." (PMID 31431614, 2019). "Mechanistically, acquisition of drug resistance enables KRAS-mutant lung cancer cells to bypass canonical KRAS effectors but entail hyperactive AXL/eIF4E, increased protein turnover in the ER, and adaptive activation of an ER stress-relief UPR survival pathway whose integrity is maintained by HSP90." (PMID 31431614, 2019). "In order to investigate whether combined targeting mTOR and Mnk/eIF4E pathway would result in augmenting growth-inhibitory effects on lung cancer cells, four human NSCLC cell lines were treated by RAD001 alone or in combination with CGP57380." (PMID 27050281, 2016). "There were highly over expression rate of eIF4E, and closely correlated with lymphnode metastasis in NSCLC, which implies that the eIF4E expression may be related to tumorgenesis, invasion and metastasis of lung cancer." (PMID 21159249, 2010). "eIF4E may be a new marker for lung cancer and objective indicators assessing the development of lung cancer." (PMID 21159249, 2010). "EIF4E and β-Catenin are key regulators of the growth and survival of lung cancer cells, and their pharmacological inhibition may have therapeutic effects on lung cancer." (PMID 37601696, 2023). "JDB153 can effectively inhibit the phosphorylation of eIF4E and VEGFR2, suppress proliferation, migration and invasion, promote apoptosis, and induce cycle arrest of lung cancer cells." (PMID 40308810, 2025). "However, the prolonged treatment of human lung cancer cells with rapalogs results in an mTOR-targeted therapy resistance through the compensatory feed-back mechanism between AKT/mTOR pathway and MNK/eIF4E pathway." (PMID 32340135, 2020). "Our finding that HSP90/AXL/eIF4E-regulated UPR fosters tumor evolution and heterogeneity provides a conceptual framework for developing rational therapeutic strategies to treat KRAS-mutant lung cancer." (PMID 31431614, 2019). "It is also conceivable that HSP90/AXL/eIF4E signaling strength, ER stress magnitudes, and UPR status may stratify subsets of patients with KRAS-mutant lung cancer who likely benefit from the combination therapy." (PMID 31431614, 2019). "Besides, we noted that co-treatment of the lung cancer cell lines with RAD001 and CGP57380 resulted in the obviously decrease expression of p-AKT protein at 24 h, at which RAD001-induced eIF4E phosphorylation was substantially inhibited by CGP57380." (PMID 27050281, 2016). "We showed that HSP90/AXL/eIF4E-regulated endoplasmic reticulum (ER) stress response, or the unfolded protein response (UPR), represents an acquired dependency and confers a selective vulnerability in drug-resistant KRAS-mutant lung cancer cells that drug-naïve parental cells lack." (PMID 31431614, 2019). "Our results provide a strong rationale for combining current chemo and anti-MEK cancer drugs with inhibitors of the HSP90/AXL/eIF4E/UPR pathway to treat KRAS-mutant lung cancer and perhaps other malignancies for which no effective therapy available for advanced diseases." (PMID 31431614, 2019).
lung carcinoma (continued). "In this study, we uncovered that AXL/eIF4E-regulated UPR signaling network, with HSP90 at the helm of the regulatory hierarchy, is an acquired dependency of and confers a selective vulnerability in KRAS-mutant lung cancer cells resistant to chemo and anti-MEK cancer drugs." (PMID 31431614, 2019).